SOX10 (SRY-box transcription factor 10)
Diseases named in the same sentence as SOX10 in open-access papers (continued):
Sharing a sentence is not in itself a finding about the gene and the disease.
tumor (continued). "We postulate that when the broadly open chromatin landscape of the early embryo is simulated in epigenetically eroded tumours, dominant fate specifiers like SOX10 may recreate their ancestral regulatory circuits by default." (PMID 35501337, 2022). "Finally, one MNST (1.5%) in our case series was compatible with a diagnosis of epithelioid MNST based on tumor cell morphology and diffuse expression of Sox10, which strongly supported such a diagnosis." (PMID 35622732, 2022). "Frequency of SOX10 staining pattern with the grade of the tumor (n = 100)." (PMID 36120242, 2022). "The goal of this study is to emphasize that SOX10 is consistently positive in TNBC with increasing grade of tumor and in diagnosing unknown primary; hence, it can be helpful for pathologists to avoid misleading diagnoses at metastatic sites." (PMID 36120242, 2022). "Consequently, the general SOX10 positivity of the tumor should be checked before inclusion in the training set." (PMID 36361209, 2022). "Immunohistochemical analyses reveal the S100-protein and SOX10 positivity of tumor cells." (PMID 35741273, 2022). "The tumor cells were positive for SOX10, S100, Melan-A, and HMB45." (PMID 36289768, 2022). "In our study, epidermis was deliberately excluded from all analyses given the resemblance between keratinocytes and some tumor cells, and because epidermis may include normal SOX10-positive melanocytes." (PMID 36361209, 2022). "The associated tumor nuclei falsely annotated as normal-cell nuclei (N = 109) were almost exclusively caused by absent (n = 96) or pale (n = 12) SOX10 staining." (PMID 36361209, 2022). "In addition, a subset of primary GSC lines retained above average SOX10 expression in vitro, confirming cell-intrinsic expression in tumour cells." (PMID 33846316, 2021). "In addition, within SOX10 OE tumours the majority of invasive tumour cells had low or undetactable SOX10 levels, whereas SOX10 high cells were found predominantly closest to the tumour bulk." (PMID 33846316, 2021). "Importantly, we also observed that tumor growth increased in the GAPDHS overexpression group compared with that in the SOX10 knockdown group, and the overexpression of GAPDHS partly rescued the impairment of tumor growth by shSOX10 in vivo." (PMID 34249897, 2021). "This might also have major implications in the targeting of tumor stem cells in TNBCs and our understanding of the role of Sox9 and Sox10 during development." (PMID 33985544, 2021). "The CD40+SOX10+ cells in each tumor biopsy ranged from 2 to 616 counts." (PMID 34092233, 2021). "In comparison, ALK amplification leading to unrestricted expression of ALK during undefined developmental stages results in the severe disruption of specification and consequent tumour formation, or death during development, as seen in Sox10::CreERT2/+; LSL-ALKF1174L mice." (PMID 34769149, 2021). "Aggressive low-grade peripheral sheath tumor cells show a curly tapered nucleus and cytological atypia and are positive for S100 and SOX10 and negative for MUC4; they show loss of expression for H3K27me." (PMID 33526082, 2021). "In addition, a subset of tumor cells had nuclear immunoreactivity for the transcription factor Sox10 (30–50% positivity)." (PMID 33707600, 2021). "Importantly, tumour cell differentiation paralleled these changes, with the number of SOX10+/EdU− tumour cells gradually increasing over time and remaining lowly proliferative, indicative of stable pre-oligodendrocyte differentiation." (PMID 33846316, 2021). "The tumor cells were strongly positive for S-100 and SOX-10 protein." (PMID 34102999, 2021). "SOX10 overexpression or treatment with myelination-promoting agents that upregulate endogenous SOX10, mimic this response, leading to niche-independent pre-oligodendrocyte differentiation and tumour suppression in vivo." (PMID 33846316, 2021). "In contrast, SOX10 expression was reduced in this tumor tissue." (PMID 34526609, 2021).
tumor (continued). "To determine whether 2XSB cells maintained the immunophenotype of the parent tumor, we stained 2XSB cells for S100β, Sox10 and nestin." (PMID 33707600, 2021). "Furthermore, activated microglia with engulfed myelin debris was frequently observed in both xenografts and human samples, and colocalised with SOX10+ tumour cells." (PMID 33846316, 2021). "Western blot analysis showed a marked increase in the levels of Sox9 S181 phosphorylation in SLK knockout tumor cell lines that was correlated with elevated Sox10 levels in these cells, suggesting increased Sox9 activity in SLK-null tumor cells compared to the control." (PMID 33985544, 2021). "In addition, immunohistochemistry staining identified increased numbers of Aif1 (Iba1) positive cells in SOX10 KD compared to control tumours." (PMID 33339831, 2020). "In pleomorphic MPNST, the tumor cells are focally positive for S100 protein and SOX10." (PMID 32867125, 2020). "Interestingly, in the ER- tumours, BMI1 showed positive association with CD133 (P < 0.0001) and SOX10 (P = 0.01) expression." (PMID 32524353, 2020). "Each tumor cell could be identified easily as a single cell because SOX-10 was stained in the nucleus." (PMID 32434572, 2020). "In extensive studies of murine neural developmental pathways and their potential role in human gliomagenesis, SOX9-dependent activation of the transcription factor nuclear factor I-A (NFIA) was shown to antagonise SOX10 function and result in astrocytic differentiation of the tumour cells." (PMID 33339831, 2020). "Tumor cells stain positive for vimentin, S-100 protein, and SOX10; neuroendocrine markers such as CD56, synaptophysin, and NSE may also be positive." (PMID 33025168, 2020). "Furthermore, the level of SOX10 is not only related to the degree of tumor progression but can also determine the stage of tumor." (PMID 33344444, 2020). "When the analysis was restricted to the luminal ER+ tumours, high BMI1 expression was associated with low expression of ALDH1A1 (P = 0.025), ALDH1A3 (P = 0.026), CD133 (P = 0.038), CD44 (P = 0.0001), CD24 (P = 0.004) and SOX10 (0.0006)." (PMID 32524353, 2020). "We confirmed that Olig2 and Sox10 are highly expressed in tumor tissue, supporting a mechanism in which oligoneural precursor transcription factors contribute to gene expression driving tumor cell proliferation." (PMID 29914980, 2018). "Likewise, homozygous deletion of Sox10 in Tyr::NrasQ61K mice not only prevented NrasQ61K-stimulated skin hyperpigmentation, but also led to hair greying in these mice." (PMID 25629959, 2015). "Although this remains to be shown, these invasive cell lines with SOX10 low/SOX9 high expression might have been established by capturing or inducing invasive tumor cells that appear to be rather rare in biopsies of bulk tumor tissue." (PMID 25629959, 2015). "Furthermore, the observation of distinct, diffuse nuclear SOX-10 expression in retinal inner and outer nuclear layers is a finding that warrants further investigation as a marker in paediatric tumours." (PMID 26316887, 2015). "Ectopic expression of SOX10 could effectively suppress tumor proliferation and metastasis in cell lines harboring wild-type as well as mutant β-catenin." (PMID 25301735, 2014). "The effect of SOX10 on tumor cell migration and invasion was further explored." (PMID 25301735, 2014). "Together, these data demonstrate that SOX10 functions as a tumor suppressor for digestive cancers." (PMID 25301735, 2014). "Our study thus validated that SOX10 is a functional tumor suppressor for digestive cancers." (PMID 25301735, 2014). "Furthermore, tumor cells with ectopic SOX10 expression migrated significantly slower than control cells, whereas introduction of SOX10-DB, -3G or -482ins6 mutants only partially suppressed tumor cell migration as by transwell assays." (PMID 25301735, 2014).
tumor (continued). "Sequence analysis indicate that SOX10 also contains a similar highly conserved motif, DVAELDQYL, which is essential to the intercation of SOX10 with β-catenin, also to the abilities of SOX10 to bind to target promoters and exert its transcriptional regulator and tumor suppressor functions." (PMID 25301735, 2014). "Also, Sox10 and S100 are routinely employed in the pathological diagnosis of neural crest-derived tumours, and Sox10 serves as an embryonic glial-lineage marker in NT’s." (PMID 23835063, 2013). "Sox9, Sox10 and Slug were expressed in 82–96% of the tumor cells prior to chemotherapy." (PMID 24404438, 2013). "Furthermore, high HSPB1 expression may have triggered EMT-related genes (SNAI1, SNAI2, SOX10), suggesting a complex dual effect of 2S-13 on tumor plasticity." (PMID 41007338, 2025). "In addition, the GSEA analysis results suggest that high expression of SOX10 may exert a pro tumor effect by inhibiting the interferon gamma (IFN-γ) response and JAK/STAT signaling pathway." (PMID 40342816, 2025). "Copy-number gains of EP300 and SOX10 were found to correlate with higher gene expression levels, suggesting that these copy-number gains have a functional consequence and may thus be biologically relevant in tumor samples." (PMID 38994683, 2024). "Moreover, these three MPNSTs presented few somatic SNVs, similar to other groups described in this tumor type (median of 40–60 variants) and presented negative SOX10 and S100B staining, as expected." (PMID 37798904, 2024). "In summary, scRNA-seq analysis indicated the Sox10-KD-dependent transition to a more neural development-like tumor phenotype, including fast-cycling proliferative and slow-cycling qNSC cell states that potentially contribute to short-term tumor growth and long-term tumor maintenance." (PMID 39285246, 2024). "Next, to evaluate whether SOX10 knockout causes alterations in the ECM in vivo, we used second-harmonic generation of polarized light microscopy to visualize polymerized/fibrous collagen bundles at the residual tumor areas." (PMID 35296667, 2022). "Importantly, time-course analysis of SOX10 levels in the tumours that eventually formed revealed that SOX10 overexpressing cells were progressively outcompeted by cells that had escaped transduction, confirming that high SOX10 levels are tumoursuppressive." (PMID 33846316, 2021). "Thus, SOX10 controls a transcriptional programme of oligodendrogenesis in tumour cells." (PMID 33846316, 2021). "Importantly, SOX10 abrogation suppressed in vivo tumor growth and proliferation." (PMID 34249897, 2021). "Thus, only SOX10-positive tumor cells were scored for PTEN expression status." (PMID 32245160, 2020). "Furthermore, Nanog and SOX2 targets may be perturbed by the SOX10 family, suggesting the importance of SOX10 in activation of cells to the MIC state at the tumor periphery." (PMID 32620903, 2020). "SOX10 may have a certain promoting effect on tumor progression." (PMID 33344444, 2020). "We thus explored whether tumor cells are functionally dependent on SOX10 inactivation." (PMID 25301735, 2014). "Interestingly, Sox10 was detected in a high percentage of tumor samples (up to 91-94%)." (PMID 24404438, 2013). "At the protein level, organoids expressed both stem/progenitor markers (nestin, vimentin, SOX10) and chromaffin differentiation markers (synaptophysin, CD56), although expression of the latter was markedly reduced compared to primary tumor tissue." (PMID 41928881, 2026). "When compared with S100 and SOX10, PRAME was demonstrated to be less sensitive but much more specific because of its limited expression in benign melanocytic lesions." (PMID 40507250, 2025).
tumor (continued). "We used comparative proximity analysis to determine the identities of cells lying within a 15 μm radius of each SOX10+ MART1− and SOX10+ MART1+ tumor cell." (PMID 40667360, 2025). "Sex determining region Y-box 10 (SOX10) is over-expressed in SKCM and reported to accelerate tumor invasion and immunosuppression." (PMID 40342816, 2025). "The tumour cells in ACiCas are very sensitive to markers like DOG-1, EMA, SOX10, and NR4A3, a novel specific marker, and are stained well." (PMID 41328110, 2025). "Among these, clusters 0, 1, 2, 3, and 7 are tumor cells that highly express MLANA, MITF, SOX10, and MKI67." (PMID 40356756, 2025). "Immunostaining of the tumor cells was positive for S-100, Melan A, HMB-45, and SOX10, consistent with MM." (PMID 41001300, 2025). "Particularly, we also found that the relapsed/resistant tumor cells expressed a signature of “Schwann cell precursors (SCP)”51,52, characterized by high expression of S100b, Sox10, Plp1 and other genes." (PMID 40962798, 2025). "Immunohistochemically, the tumor cells were diffusely positive for PRAME and SOX10, focally positive for Melan-A, and very focally positive for HMB45." (PMID 40437181, 2025). "Immunohistochemistry results were as follows: CD117 (+), CD34 (+), Desmin (-), DOG-1 (+), Ki67 positivity in approximately 5% of tumor cells, S-100 (-), SDHB (+), SMA (few cells +), SOX-10 (-)." (PMID 40365338, 2025). "Immunohistochemical examination showed that tumor cells were strongly positive for vimentin, SMA, and P16 but negative for desmin, CK, P40, P63, CK5, HMB45, MyoD1, myogenin, S100, and SOX10." (PMID 39872225, 2025). "Immunophenotyping found tumor cells that were CK (+), CD56 (+), Syn (+), EMA (+), β-catenin (membrane +), LCA (−), CD99 (−), S100 (−), HMB-45 (−), SOX-10 (−), TTF-1 (−), CDX-2 (−), and CD34 (−), along with a Ki-67 proliferation index of 60–70%." (PMID 41245381, 2025). "Immunohistochemical profiling showed CD117 (+), CD34 (+), Desmin (-), DOG-1 (+), Ki67 (approximately 5% positive tumor cells), S-100 (-), SDHB (+), SMA (a few cells +), and SOX-10 (-)." (PMID 40365338, 2025). "By IHC, the tumor cells consistently expressed EMA (20 of 21) and CKAE1/3 (16 of 22), in combination with S100 (21 of 22) or SOX10 (9 of 19)." (PMID 39636306, 2025). "Although the tumor cells uniformly expressed HMGA2 protein in all cases, cytokeratin 7, S100 protein, and SOX10 displayed either diffuse positivity or highlighted the luminal and abluminal cell populations, respectively." (PMID 40033554, 2025). "Immunohistochemical detection of the expression of S-100, SOX10, and GFAP in tumour cells can assist in differential diagnosis." (PMID 41357577, 2025). "Taken together, our results demonstrated that clones in the same tumor can naturally express less PRDX1, MITF, SOX10, PGC-1α, and pigmentation markers." (PMID 38790661, 2024). "SOX10 and PRAME resulted positive in all tumor cells, whereas the other melanocytic markers showed extreme heterogeneity." (PMID 38191367, 2024). "In these cases, markers such as GATA3, SOX10, mammaglobin, GCDFP15, ER, PR, HER2, and basal markers (e.g., CK5/6) should be included to provide a more complete picture of the tumor’s origin and subtype." (PMID 39518009, 2024). "Immunohistochemically, the tumour cells were diffusely positive for CK7, S-100, p63, SOX10 protein and focally positive for SMA protein and completely negative for CK20, p40, Mammaglobin, CD117 and GCDFP15." (PMID 38982505, 2024). "The tumor with melanin production was immunohistochemically positive for S-100, HMG-45, Melan-A, and SOX10." (PMID 38289480, 2024). "Immunoistochemically, both benign and malignant tumor cells typically stain positively for S-100, CD68, neuron-specific enolase, CD57, inhibin, calretinin, TFE3, SOX10, and nestin." (PMID 39372871, 2024). "Immunohistochemical results indicate the expression of pan-cytokeratin (AE1/AE3, Ventana) and SOX10 (clone SP267, Ventana) by tumor cells, confirming breast carcinoma." (PMID 39628747, 2024).
tumor (continued). "The pathology showed the tumor cells to be positive for cytokeratin (CK), Vimentin, EMA, CD34, cyclinD1, negative for CK8, CK19, CK20, SMA, Desmin, S-100, CD117, Dog-1, Hepar-1, SOX-10 and ALK, and Ki-67 approximately 50%, which confirmed the diagnosis of SHC." (PMID 38552058, 2024). "Sox10, a transcriptional activator is highly expressed in BLBC, which is critical for tumor progression." (PMID 38654332, 2024). "Immunohistochemically, the tumor is positive for S100, CD34, and SOX-10 and has an H3K27me3 expression deletion." (PMID 39345656, 2024). "Pan-Trk immunoreactivity is associated with a fusion partner-specific pattern of staining NTRK-rearranged tumours also commonly express CD34, often with coexpression of S100, but lack SOX10 expression." (PMID 38151535, 2024). "The differential expression of SOX10, GATA3, and TTF-1 is usually helpful in determining the tumor origin." (PMID 38813332, 2024). "Immunohistochemically (IHC), tumor cells were positive for SMA, MDM2, and p16; the cells were negative for desmin, MyoD1, Myogenin, pan-cytokeratin, S100, SOX10, HMB45, Malen-A, CD34, CD31, CD99, and ALK." (PMID 37735390, 2023). "Immunohistochemically, tumor cells were positive for CK, EMA, Vimentin, CD117, CK7, S100, Mammaglobin and SOX10." (PMID 37803309, 2023). "Immunohistochemical staining revealed that the tumor cells were positive for S-100, CD68, SMA, SOX-10, Calretinin, and TFE3." (PMID 37840916, 2023). "SOX10 knockout in immune-competent models leads to reduced expression of immune checkpoint proteins HVEM and CEACAM1, facilitating tumor growth." (PMID 38132479, 2023). "As a result, evaluating the whole tumor sample or at least 2.37 mm2 of tumor is critical when assessing PXN and Sox-10 reactivity." (PMID 36669002, 2022). "Immunohistochemically, the tumor showed positivity for MART1, HMB45, collagen IV, and SOX10, and negativity for AE1/AE3." (PMID 35902891, 2022). "Analysing published cell line gene expression and methylation array datasets and our cell line bank, we found that in contrast to tumours, TNBC cell lines express very low to undetectable levels of SOX10, and the SOX10 gene is hypermethylated." (PMID 35501337, 2022). "Tumor cells stained positive for SOX10, S-100 (10% of tumor), with a "mosaic pattern" of H3K27ME3 (50% of tumor nuclei positive)." (PMID 36654587, 2022). "Specifically, in magenta, a subset of neural crest progenitor markers, such as NES, SOX10, ERBB3, and NGFR, were reported as highly expressed markers of Schwann cell progenitors and the signatures of stem-like tumor cells in NF1 tumors." (PMID 35741605, 2022). "Immunophenotyping revealed consistent negativity for the melanocytic markers MART-1 and HMB-45, while S100, SOX-10 and PRAME showed nuclear positivity in all tumor parts including the dedifferentiated area." (PMID 35645230, 2022). "We also used specific tumor markers to identify the organoids derived from specific subtypes of SGTs, e.g. MUC4 was used to identify MEC, DOG1 and SOX10 were used to identify AciCC, and HER2 and AR were applied to identify SDC." (PMID 36527158, 2022). "In this study, we performed several immunohistochemical stainings, including S-100 protein, SOX-10, CD68, desmin, DOG-1, AE1/AE3, P63 and Ki-67, which are used as ancillary tests for diagnosis of the tumor." (PMID 34243786, 2021). "To establish a potential link with active Sox9 in Sox10+ human samples, we assessed the levels of pSox9 S181 and Sox10 by immunohistochemistry across HER2-positive, luminal, and TNBC tumor cores." (PMID 33985544, 2021). "This analysis revealed that tumor cells were positive for S-100 protein, HMB-45, Melan-A, and SOX10." (PMID 33478436, 2021). "SOX10 knockout reduces the rate of CD24–/CD44+ cells and cancer stem cell properties, which ultimately inhibits tumor formation." (PMID 33344444, 2020).